TAF1B (TATA-box binding protein associated factor, RNA polymerase I subunit B)
Description:
Component of RNA polymerase I core factor complex that acts as a GTF2B/TFIIB-like factor and plays a key role in multiple steps during transcription initiation such as pre-initiation complex (PIC) assembly and postpolymerase recruitment events in polymerase I (Pol I) transcription. Binds rDNA promoters and plays a role in Pol I recruitment as a component of the SL1/TIF-IB complex and, possibly, directly through its interaction with RRN3.
Synonyms: TAFI63; SL1; RAF1B; RAFI63; MGC:9349
Tractability: PROTAC: ubiquitination databases record sites on it.
Gene: Protein-coding gene on chromosome 2 (9,843,443 to 9,934,416, forward strand). Ensembl gene ENSG00000115750.
Subcellular location: Nucleus, nucleolus
Subcellular location (Human Protein Atlas): Nucleoli; Nucleoplasm
Pathways (Reactome):
Gene expression (Transcription): B-WICH complex positively regulates rRNA expression; NoRC negatively regulates rRNA expression; RNA Polymerase I Promoter Escape; RNA Polymerase I Transcription Initiation; RNA Polymerase I Transcription Termination; SIRT1 negatively regulates rRNA expression
Gene Ontology:
Molecular function: protein binding; RNA polymerase I core promoter sequence-specific DNA binding; TBP-class protein binding
Biological process: regulation of DNA-templated transcription; RNA polymerase I preinitiation complex assembly; DNA-templated transcription; nucleolar large rRNA transcription by RNA polymerase I; transcription by RNA polymerase I
Cellular component: nucleolus; RNA polymerase I core factor complex; RNA polymerase transcription factor SL1 complex; nucleoplasm; nucleus; RNA polymerase I transcription regulator complex
Genetic constraint (gnomAD): Loss-of-function variants: 38 observed, 68.27 expected, observed/expected ratio (o/e) 0.56, 90% interval 0.43 to 0.73. The upper end of that interval is the gene's LOEUF score, 0.73, which puts it in group 2 of 6, group 1 being the genes least tolerant of losing a copy. Missense variants: 545 observed, 607.13 expected, observed/expected ratio (o/e) 0.9, 90% interval 0.84 to 0.96. Synonymous variants: 197 observed, 209.07 expected, observed/expected ratio (o/e) 0.94, 90% interval 0.84 to 1.06.
Homologues: Orthologues: chimpanzee TAF1B (99% identical), macaque TAF1B (96% identical), dog TAF1B (83% identical), pig TAF1B (82% identical), rabbit TAF1B (79% identical), mouse Taf1b (74% identical), guinea pig TAF1B (74% identical), rat Taf1b (74% identical), tropical clawed frog taf1b (46% identical), zebrafish taf1b (36% identical), Drosophila melanogaster TAF1B (19% identical).
Diseases named in the same sentence as TAF1B in open-access papers:
TAF1B is named in the same sentence as 19 diseases in open-access papers, as found by Europe PMC text mining. Sharing a sentence is not in itself a finding about the gene and the disease. The quoted sentences say what the papers report.
breast carcinoma (1 paper, 2022). "Additionally, we observed downregulation of genes such as POLR1A, POLR1D, POLR1E, TAF1B, LAMP1, and CDKN1A in response to AQ treatment demonstrating the role of AQ in regulating RNA polymerase subunits and effect on overall gene transcription in breast cancer." (PMID 36232751, 2022).
chronic lymphocytic leukemia (1 paper, 2022). "For example, TAF1B was predicted to be a common inhibitory therapeutic target for ATL, endometrial cancer, T1DM, HC, testicular cancer, tuberculosis and chronic lymphocytic leukemia." (PMID 35758779, 2022).
glaucoma (1 paper, 2022). Increased pressure in the eyeball due to obstruction of the outflow of aqueous humor. "Twelve of these genes, including PTPRB, HFM1, TAF1B, AAK1, FOXD1, EHMT1, and DNTT, are associated with glaucoma topical treatments (P < 1 × 10−5)." (PMID 36450729, 2022).
hepatocellular carcinoma (1 paper, 2023). A malignant tumor that arises from hepatocytes. "We identified that TAF1B was highly expressed in hepatocellular carcinoma and associated with poor prognosis in HCC patients." (PMID 37645431, 2023). "These discoveries suggested that TAF1B depletion effectively inhibited the viability of hepatocellular carcinoma cells and significantly promoted apoptosis." (PMID 37645431, 2023). "We analyzed the differential expression and prognostic value of TAF1B in hepatocellular carcinoma based on The Cancer Genome Atlas (TCGA) database, tumor and paraneoplastic tissue samples from clinical hepatocellular carcinoma patients, and typical hepatocellular carcinoma." (PMID 37645431, 2023). "According to our findings of the significant high expression of TAF1B in hepatocellular carcinoma tissues and its poor prognosis, we conclude that targeting TAF1B may give another method of treating malignancies by interfering with the transcriptional activity of Pol I." (PMID 37645431, 2023). "Next, we investigated whether TAF1B is crucial for the survival of hepatocellular cancer cells." (PMID 37645431, 2023). "However, the function of TAF1B in the progression of hepatocellular carcinoma (HCC) is unknown." (PMID 37645431, 2023).
leukemia (1 paper, 2022). A malignant (clonal) hematologic disorder, involving hematopoietic stem cells and characterized by the presence of primitive or atypical myeloid or lymphoid cells in the bone marrow and the blood. "Here, we tested the expression of Taf1b and Nom1 in normal and leukemia cells following treatment with SD49-7." (PMID 35836814, 2022). "In this study, we found that the expression of Taf1b and Nom1, downstream of KDM4s, was not affected by SD49-7 in MLL-AF9 GFP+ and THP-1 cells, indicating that KDM4 regulated different downstream genes in leukemia and normal cells." (PMID 35836814, 2022). "However, these inhibitors did not decrease the expression of Taf1b and Nom1 in both MLL-AF9 GFP+ cells and THP-1 cells, indicating that KDM4 regulated different downstream genes in leukemia and normal cells." (PMID 35836814, 2022).
Salmonella Infections (1 paper, 2011). Infections with bacteria of the genus SALMONELLA. "Other top-ranked differentially expressed genes in the LS1 pigs such as KRTAP11-1, TAF1B and BTBD10, have not been associated with Salmonella infection previously." (PMID 22174891, 2011).
uterine corpus endometrial carcinoma (1 paper, 2023). A endometrial carcinoma (disease) that involves the body of uterus. "Using a series of 543 uterine corpus endometrial carcinoma (UCEC) issued from the TCGA database, a significant association was observed for NHP2 (P = 0.0003) and TAF1B (P = 0.034), but not for Nop10 (P = 0.77), − high levels of NHP2 and TAF1B being associated with the poorest outcome." (PMID 36370117, 2023).
tumor (2 papers, 2020 to 2023). "The results indicated a significant increase in TAF1B staining intensity in tumor tissues compared to paracancerous tissues." (PMID 37645431, 2023). "Finally, we examined the effect of TAF1B inhibition on tumor development in vivo." (PMID 37645431, 2023). "In addition, the size and weight of the tumors formed by the tumor cells lacking TAF1B were considerably decreased." (PMID 37645431, 2023).
cancer (1 paper, 2023). A tumor composed of atypical neoplastic, often pleomorphic cells that invade other tissues. "Taken together, we found TAF1B was crucial for Pol I function and the cancer progression in HCC." (PMID 37645431, 2023).
lip (1 paper, 2019). "FOXF2 (rs2814820; p-value 3.90 × 10− 6) and TAF1B (rs1003652; p-value 4.54 × 10− 6) are near a cleft lip and cleft lip and palate risk loci, respectively." (PMID 31533690, 2019).
TAF1B also shares sentences with these, for which no sentence is quoted: endometrial cancer (1 paper); Hepatitis (1); influenza (1); lymphoma (1); measles (1); Schwachman Diamond syndrome (1); testicular cancer (1); Treacher-Collins syndrome (1); tuberculosis (1).